HUWE1 (HECT, UBA and WWE domain containing E3 ubiquitin protein ligase 1)
Diseases named in the same sentence as HUWE1 in open-access papers (continued):
Sharing a sentence is not in itself a finding about the gene and the disease.
tumor (continued). "While HUWE1, UBR5, PRPF19, ARIH2 and OBI1 are mainly related to tumor suppression, DNA damage response and DNA replication, TRIM21 is involved in regulating host innate immunity and viral immune evasion." (PMID 38932241, 2024). "Among them, TAZ was up-regulated in tumor tissue compared with para-cancerous tissue, and the expression of the remaining eight genes (including SLC25A4, SLC25A5, PARK, PINK1, MFN2, HUWE1, VPS13D, and LRBA) was down-regulated in tumor tissue." (PMID 38373978, 2024). "MDM2 was also reported to mediate HUWE1 degradation and in turn regulate the abundance of Mcl1 and PP5 to contribute to tumor cell drug resistance." (PMID 35937685, 2022). "E3 ligase MDM2, PARKIN and HUWE1 can catalyze ubiquitination of HIF-1α and targets it for degradation, thus exerting an anti-tumor effect." (PMID 33004065, 2020). "Immunohistochemical analysis of CD138/HUWE1 and CD138/MYC validated HUWE1 knockdown in vivo and demonstrated reduction in MYC expression and tumor burden 13 days post-treatment with doxycycline, lenalidomide or a combination of both." (PMID 32523091, 2020). "Quantitative proteomic analysis reveals the upregulation of E3 Ubiquitin ligase HUWE1 and DUBs like USP9X and UBP7 in both tumor and metastatic lesions, which is further confirmed in additional patients." (PMID 32345963, 2020). "HUWE1 is a HECT domain-containing E3 ubiquitin ligase that regulates the stability of various cellular targets and has been shown to exhibit both tumor suppressor and oncogenic functions." (PMID 32345963, 2020). "Our data show that expression of HUWE1, USP9X and USP7 are higher in the tumor and metastatic lesions of many patients, compared to matched normal tissue irrespective of their mutational status." (PMID 32345963, 2020). "In order to test our proteomics observations in a larger cohort of patient samples, we analyzed the expression of HUWE1, USP9X and USP7 in protein lysates isolated from fresh frozen PTC patient samples (7 normal, 8 tumor, 3 metastatic lesions)." (PMID 32345963, 2020). "Seven-mutated genes detected from bcWES data are detected in single cells of either primary tumor or lymph node (fdr2d<0.2): MT-RNR2, MT-RNR1, MT-ND5, MT-TI, HUWE1, TMEM219 and INTS8." (PMID 31028395, 2019). "As previously demonstrated, mitochondria are fundamental in cellular homoeostasis and the HUWE1–AMBRA1 axis can represent a focal point of interconnection between healthy and tumour cells." (PMID 30217973, 2018). "HUWE1 is an E3 ubiquitin ligase that controls the stability of MCL1, MYC and MYCN functions which would suggest a tumour‐suppressive role." (PMID 28003334, 2017). "It has been shown that the E3 ligase activity of HUWE1 can be inhibited by Alternative reading frame (ARF), a tumor suppressor that can be activated through hyperproliferative signals." (PMID 25883150, 2015). "Here, we demonstrate that acetylation of YEATS4 by the histone acetyltransferase KAT8 stabilizes YEATS4 via impairing its binding to E3 ligase HUWE1 and promotes BC tumor growth and that targeting the KAT8/YEATS4 axis suppresses tumor growth and sensitizes BC cells to cisplatin." (PMID 38526153, 2024). "HUWE1 is not a commonly mutated cancer gene; indeed HUWE1 mutations are rare in the population as a whole and CRISPR-Cas9 mutagenesis of HUWE1 in > 900 tumour cell lines (in the DepMap dataset) suggest that complete loss-of-function is lethal." (PMID 37491606, 2023).
tumor (continued). "Observations made with BET inhibitors JQ1 or OTX015 targeting both c-MYC and MYCN warrant additional studies using MYCN specific inhibition such as HUWE1 inhibitors or specific knockdown to differentiate the relative importance of c-MYC and MYCN in ATL tumor cells survival and proliferation." (PMID 32907612, 2020). "Finally, as HIF-1α plays a major role in inducing tumor progression, K63-polyubiquination of HAUSP mediated by HUWE1 would contribute to the oncogenic function of HUWE1." (PMID 30176860, 2018). "This indicates that HUWE1 suppresses intestinal tumourigenic at multiple levels, in part by stopping tumour initiation but (and consistent with the data on MYC above) also at the level of tumour growth." (PMID 28003334, 2017). "However, via K63‐mediated ubiquitination, HUWE1 is required for the transactivation function of MYC and tumour cell proliferation." (PMID 28003334, 2017). "Specifically, a group of 40 well-defined genes, classified according to their function, were able to distinguish between 2 different GBM signatures revealing the possible different proliferative potential in high grade GBM tumours (VIM, GLUL, PLK1, HUWE1, RPS4X...)." (PMID 20735813, 2010). "Besides, dysregulation in post-transcriptional modifications, like ubiquitination enzymes (HUWE1, CUL4A, TRIM25, etc.)and deubiquitination enzymes (USP7, USP10, USP24, etc.)in these PTC tumor samples may also lead to the low consistency." (PMID 38609408, 2024). "However, despite the enhanced survival, Vil Apc Pten Huwe1 Myc mice showed no reduction in tumour number." (PMID 28003334, 2017). "Data showing a role for the ubiquitin ligases β-TrCP, FBW7, Huwe1, and SKP2 in MBs suggest the possibility of a classification of MBs based on the expression (over expression or under expression) of specific ubiquitin ligases which function as oncogenes, tumor suppressors or cell cycle regulators." (PMID 26475605, 2015). "Moreover,once developed, such HUWE1-targeting agents may have to be used in combination with other drugs, asknockdown of HUWE1 alone is not sufficient to induce tumor regression." (PMID 25368331, 2014). "However, it is also clear from our work, and others, that MYC levels are sufficiently high for transformation in the presence of HUWE1 and reduction or overexpression of MYC does not have a profound impact on tumour initiation." (PMID 28003334, 2017).
cancer (59 papers, 2007 to 2026). A tumor composed of atypical neoplastic, often pleomorphic cells that invade other tissues. "Through genetic and proteomic screening, we identify UBR4, UBR5, and HUWE1 as key ubiquitin E3 ligases marking cancer-associated A3B and A3H-I for degradation, thereby limiting A3-driven hypermutation." (PMID 41554709, 2026). "Gp78 also exhibits a distinct cancer specific expression profile relative to other cancer-associated mitophagy inducers such as HUWE1, BNIP and NIX." (PMID 36284011, 2022). "The HECT type E3 ligase HUWE1 is highly associated with DNA repair through its ubiquitination functions in cancer development." (PMID 35006464, 2021). "HUWE1 is an X‐linked E3 ubiquitin ligase mutated at moderate frequencies (up to 15%) in a wide range of cancers including colorectal, uterine, gastric, cervical, melanoma and lung." (PMID 28003334, 2017). "Using animal cancer models, we demonstrate that Huwe1 is a key tumour suppressor gene whose loss drives increased DNA damage." (PMID 28003334, 2017). "Finally, we summarize the clinical relevance, the underlying challenges of expanding the atlas of HUWE1 substrates and the possible application of HUWE1 in cancer therapeutics." (PMID 30176860, 2018). "We propose a model, in which the activity of HUWE1 underlies conformational control in response to physiological cues—a mechanism that may be exploited for cancer therapy." (PMID 28193319, 2017). "As ‘Evading Apoptosis’ is as a fundamental hallmark of cancer and the mechanistic link between HUWE1 and apoptosis is dominant, we hypothesize that the relationship between HUWE1 and intrinsic apoptosis is rate limiting in determining the cellular responsiveness to platins." (PMID 34065298, 2021). "This highlights the context-dependent role of TGF-beta signaling in cancer progression, as its down-regulation via HUWE-1 promotes metastasis." (PMID 41385185, 2025). "Beyond these co-opted E3 ligases, we identified 363 (33.8%) potentially novel E3 ligases highly expressed in over 30 cancer types, such as HUWE1 and FBXO7, indicating the high potential of these E3 ligases for pan-cancer usage." (PMID 37845222, 2023). "According to currently available studies, HUWE1 plays a key role in regulating autophagy and other biological functions in many cancers, including DNA damage response, transcription, autophagy, apoptosis, and metabolism." (PMID 35874628, 2022). "In this review, we summarize the known substrates and pleiotropic functions of HUWE1 in different types of cells and models, including its involvement in development, cancer, neuronal disorder and infectious disease." (PMID 35937685, 2022). "Substrate specificity is achieved through E3 ligases, and a wide survey of E3 ligase dysregulation in cancer revealed HUWE1 as a significantly correlated prognostic factor." (PMID 35937685, 2022). "The HUWE1 protein has become an attractive potential therapeutic target for treating cancer and other diseases, and structural analysis will significantly advance the development of activity inhibitors with substrate-selective recruitment." (PMID 35937685, 2022). "Based on our findings, however, further studies are warranted on the contributions of HUWE1-mediated autophagic protein ubiquitination to cancer progression and treatment response." (PMID 34502089, 2021). "HUWE1 is a multifunction protein that affects several hallmarks of cancer including proliferation/differentiation, DNA repair, stress response and apoptosis pathways." (PMID 33633150, 2021). "Overall, our data indicates that modulation of ATG101 protein levels by HUWE1-mediated ubiquitination and ensuing changes in autophagy activity influence the survival of cancer cells under metabolic stress." (PMID 34502089, 2021).
cancer (continued). "Prior independent research shows that HUWE1 plays an important role in cancer tumorigenesis and metastasis, including breast cancer." (PMID 33633150, 2021). "HUWE1 was identified as an upstream E3 ligase catalyzing ATG101 ubiquitination in cancer cell lines based on the substantial reduction in ubiquitinated ATG101 upon HUWE1 KD." (PMID 34502089, 2021). "Protein levels of ATG101 was more stable and the related-autophagy activity was higher in HUWE1-depleted cancer cells compared to wild type (WT) controls, indicating that HUWE1-mediated ubiquitination promotes ATG101 degradation." (PMID 34502089, 2021). "Our data thus support findings in other cancer entities showing a role for HUWE1 for malignant growth." (PMID 33116152, 2020). "It has been proposed that the dual role of HUWE1 in cancer is influenced by different protein adaptors or post‐translational modifications." (PMID 31441992, 2019). "Being one of the well-known substrates of HUWE1, Myc provides the major pro-proliferative signaling for cancer cells and indeed, several avenues to block Myc and its signaling transduction have been designed." (PMID 30176860, 2018). "In cancer, HUWE1 targets tumor suppressor proteins, such as the checkpoint protein TopBP1 and the apoptosis-related protein Mcl1, for proteasomal degradation." (PMID 30261639, 2018). "Regardless of the exact mechanism involved, the observation that loss of dHUWE1 resulted in apoptosis is consistent with results regarding the function of HUWE1 as observed in cancer cells." (PMID 30261639, 2018). "The HECT-type ubiquitin ligase HECT, UBA and WWE Domain Containing 1, (HUWE1) regulates key cancer-related pathways, including the Myc oncogene." (PMID 30261639, 2018). "The oncogenic or suppressive functions of HUWE1 in cancer are context dependent, as HUWE1 ubiquitinates and enhances c-Myc transcriptional activity, which promotes tumorigenesis." (PMID 30261639, 2018). "HUWE1 is a HECT domain containing ubiquitin ligase implicated in neurogenesis, spermatogenesis and cancer development." (PMID 27901130, 2016). "Collectively, these results identify CRL4B as an essential E3 ligase in targeting the proteasomal degradation of HUWE1 in response to DNA damage, and provide a potential strategy for cancer therapy by targeting HUWE1 and the CUL4B E3 ligase." (PMID 25883150, 2015). "This study sheds light on the mechanism through which HUWE1 is regulated in response to DNA damage, and has important implications for cancer therapy." (PMID 25883150, 2015). "We show here that HUWE1 is required for growth ofcolorectal cancer cells in culture and in orthotopic xenograft models." (PMID 25253726, 2014). "Other candidates, such as SMARCA1, KDM6B, IRF2, PLK4, and HUWE1, may well have functional relevance to cancer development in particular cancer types, and be worthy of further investigation." (PMID 40514689, 2025). "Similarly, other members of the HECT E3 family, such as HECTD3 and HUWE1, have also demonstrated the ability to play dual roles across different cancer types, reinforcing the importance of cellular context in determining their function." (PMID 41385185, 2025). "Moreover, enhanced autophagy in HUWE1-depleted cancer cells was reversed by siRNA-mediated ATG101 knockdown." (PMID 34502089, 2021). "Ultimately, HUWE1 might serve as a clinical biomarker to tailor cancer treatment strategies, thereby improving cancer care and patient outcomes." (PMID 34065298, 2021).
cancer (continued). "Finally, we demonstrated that ATG101-mediated autophagy facilitated while ATG101 downregulation by HUWE1-mediated ubiquitination impaired cancer cell survival." (PMID 34502089, 2021). "However, HUWE1 contains a WWE domain and a ubiquitin-associated (UBA) domain, which affects various aspects of cancer development." (PMID 35006464, 2021). "Accordingly, we examined whether increased autophagy in HUWE1-depleted cancer cells could be suppressed by knockdown of WIPI2 as well as by ATG101 knockdown." (PMID 34502089, 2021). "Moreover, knockdown of HUWE1 enhanced the rate of LC3 puncta formation in cancer cells under metabolic stress, indicating that this regulatory mechanism for ATG101 levels directly modulates autophagy." (PMID 34502089, 2021). "Ultimately, HUWE1 might serve as a clinical biomarker to tailor cancer treatment strategies or for the development of new drugs, thereby improving cancer care and patient outcomes." (PMID 34065298, 2021). "HUWE1 may influence cancer metabolism and tumor progression by promoting mitophagy through MFN2 ubiquitylation." (PMID 31441992, 2019). "Together, these studies produce contrasting predictions, one where HUWE1 may drive cancer via activation of MYC function and one where loss of HUWE1 would promote cancer by increasing levels of MYC, DNA damage and genomic instability." (PMID 28003334, 2017). "Among many cancer types, CRC harbours the highest frequency of HUWE1 mutations (Fig EV1B)." (PMID 28003334, 2017). "However, the relevance of this model to human cancer is unclear as HUWE1 mutations have not yet been observed in the currently limited, cutaneous squamous cell carcinoma sequencing studies." (PMID 28003334, 2017). "Of note, we did not observe any invasive carcinomas in our Apcfl/+Huwe1‐deficient mice." (PMID 28003334, 2017). "Interestingly, several observations link Huwe1 function to cancer." (PMID 27552055, 2016). "Immunofluorescence analysis also revealed that there was a strong colocalization of JMJD5, HUWE1, and EGFR in cancer cells." (PMID 37813845, 2023). "In cancer cells, HUWE1 targets the ubiquitination and degradation of the C-terminal region of ATG101, inhibiting autophagy activity to reduce cancer cell survival." (PMID 35806307, 2022). "In summary, our study revealed two regulators of PD-L1, namely, TMUB1 and HUWE1, and connected TMUB1 with immune evasion by cancer cells." (PMID 36376293, 2022). "Our results demonstrate that HUWE1 destabilizes ATG101 by poly-ubiquitination at the C-terminus, thereby suppressing ATG101-mediated autophagy activity and further inhibiting cancer cell survival under nutrient deprivation conditions." (PMID 34502089, 2021). "Collectively, these results suggest that HUWE1 normally serves to suppress autophagy by ubiquitinating and triggering degradation of ATG101 and WIPI2, which in turn represses the survival of cancer cells." (PMID 34502089, 2021). "Thus, a direct downregulation of HUWE1 by antisense oligonucleotide (ASO) therapy delivered with nanoparticles to enhance transfection efficiency may be further applied in therapeutic intervention of cancer." (PMID 30176860, 2018). "In our study, we found that the depletion or the inactivation of CUL4B resulted in the accumulation of HUWE1, and thereby accelerated the degradation of its substrate, MCL-1, rendering cancer cells sensitive to DNA damage agents." (PMID 25883150, 2015). "Others have cancer-relevant functions, such as steroid hormone synthesis (HSD17B8, earlier), and covalent modification of histones (HUWE1, IPO7, MLL4, PAXIP1, PRKAA2, all later except PAXIP1)." (PMID 23762276, 2013).
cancer (continued). "Finally, the enhanced crosslinking and immunoprecipitation (eCLIP) analyses reveal that FXR1 binds with the G4-enriched mRNA targets such as AHNAK, MAP1B, AHNAK2, HUWE1, DYNC1H1 and UBR4 and controls its mRNA expression in cancer cells." (PMID 38709899, 2024). "Due to this reciprocal regulation of ATG101 and HUWE1, ATG101-mediated autophagy activation under HUWE1 depletion may overcome the metabolic stressors frequently encountered by cancer cells." (PMID 34502089, 2021). "To assess the expression of Gp78 in multiple cancers, we used GEPIA-2 analysis to probe TCGA RNAseq data for mRNA expression of Gp78 and other ubiquitin ligases that induce mitophagy (PARK2, RNF185, MUL1, MARCH5, HUWE1, SIAH1) as well as the hypoxia-induced mitophagy proteins BNIP and NIX." (PMID 36284011, 2022). "However, the precise functions of HUWE1 in cancer progression are controversial, as they are determined not only by the physiological functions of target substrates, but also by other types of post-translational modifications." (PMID 34502089, 2021). "In addition, HUWE1 has also been shown to be required for the promotion of cell survival and tumorigenesis, through the K63-linkage ubiquitination of c-MYC and hence its activation in cancer cells." (PMID 25883150, 2015). "HUWE1 revealed exclusively monoallelic enrichment for all three marks, consistent with its silence on the Xi in all lines, whereas escapees SMC1A and DDX3X and several “cancer-specific” escapees displayed biallelic H3K4me3 and RNA Pol II, with monoallelic H3K27me3." (PMID 25653311, 2015). "Our observations concur with the expected expression profiles in the two normal and three cancer cell lines, i.e., KDM5C is expressed from all X chromosome fragments that carried the gene, and HUWE1 is expressed only from the non-XIST RNA-coated X fragments that carried it." (PMID 25653311, 2015).